MZF1 (myeloid zinc finger 1)
Description:
Binds to target promoter DNA and functions as a transcription regulator. Regulates transcription from the PADI1 and CDH2 promoter. May be one regulator of transcriptional events during hemopoietic development.
Synonyms: MZF-1; ZNF42; ZSCAN6; MZF1B; Zfp98
Tractability: PROTAC: UniProt records ubiquitination sites on it.
Gene: Protein-coding gene on chromosome 19 (58,561,915 to 58,573,597, reverse strand). Ensembl gene ENSG00000099326.
Subcellular location: Nucleus
Subcellular location (Human Protein Atlas): Nucleoplasm
Gene Ontology:
Molecular function: DNA-binding transcription activator activity, RNA polymerase II-specific; DNA-binding transcription repressor activity, RNA polymerase II-specific; protein binding; protein homodimerization activity; RNA polymerase II cis-regulatory region sequence-specific DNA binding; transcription cis-regulatory region binding; DNA-binding transcription factor activity; DNA-binding transcription factor activity, RNA polymerase II-specific; identical protein binding
Biological process: negative regulation of transcription by RNA polymerase II; positive regulation of transcription by RNA polymerase II; regulation of DNA-templated transcription
Cellular component: nucleoplasm; nucleus
Genetic constraint (gnomAD): Loss-of-function variants: 26 observed, 30.58 expected, observed/expected ratio (o/e) 0.85, 90% interval 0.62 to 1.18. The synonymous counts are far from expectation, so gnomAD's model fits this gene poorly and the ratio says little. Missense variants: 1,166 observed, 979.97 expected, observed/expected ratio (o/e) 1.19, 90% interval 1.13 to 1.25. Synonymous variants: 516 observed, 395.4 expected, observed/expected ratio (o/e) 1.3, 90% interval 1.21 to 1.4.
Homologues: Orthologues: chimpanzee MZF1 (99% identical), pig MZF1 (86% identical), dog MZF1 (86% identical), rat Mzf1 (83% identical), mouse Mzf1 (83% identical), guinea pig MZF1 (71% identical). Paralogues in human: ZNF33B (27% identical), ZNF606 (27% identical), ZNF7 (27% identical), ZNF835 (27% identical), ZNF250 (27% identical), ZNF189 (27% identical), ZNF227 (27% identical), ZNF182 (26% identical), ZNF568 (26% identical), ZNF658 (26% identical), ZNF235 (26% identical), ZNF30 (26% identical), and 164 more.
Diseases named in the same sentence as MZF1 in open-access papers:
MZF1 is named in the same sentence as 79 diseases in open-access papers, as found by Europe PMC text mining. Sharing a sentence is not in itself a finding about the gene and the disease. The quoted sentences say what the papers report.
breast carcinoma (17 papers, 2016 to 2025). "The prognostic analysis in breast cancer revealed that MZF1 expression is significantly associated with the prognosis of multiple cancer types." (PMID 40655141, 2025). "Association of MZF1 and Elk1 via the acidic domain of MZF1 and the heparin-binding domain of Elk1 increases invasion, migration and mesenchymal phenotype of breast cancer cells." (PMID 31963147, 2020). "Further research has established a clear association between MZF1 and the progression of various solid tumors, where it facilitates the growth, migration, and invasion of cancer cells in breast cancer, liver cancer, lung adenocarcinoma, gastric cancer, and others." (PMID 40655141, 2025). "The resulting visualization revealed that the cancers most strongly associated with MZF1 included breast cancer, gastric cancer, hepatocellular carcinoma, neoplasm, Nijmegen breakage syndrome, non-small cell lung carcinoma, prostate cancer, and triple-negative breast cancer." (PMID 40655141, 2025). "Identifying MZF1 and let-7 as regulators of lysosome distribution in invasive breast cancer cells, uncouples cancer-associated, invasion-promoting lysosomal alterations from normal lysosomal functions and thus opens up new possibilities for the therapeutic targeting of cancer lysosomes." (PMID 29396433, 2018). "In particular, in the context of breast cancer, the value of MZF1 as a potential molecular marker has been preliminarily validated." (PMID 40655141, 2025). "Subsequently, IHC was utilized to examine the differential expression of MZF1 protein in gastric adenocarcinoma, breast cancer, and normal tissues." (PMID 40655141, 2025). "Molecular docking identified MZF1-targeted drugs, with validated effects on breast cancer and gastric cancer cell survival and migration in vitro." (PMID 40655141, 2025). "In summary, this study provides a comprehensive analysis of the potential role of MZF1 across various cancers, underscoring its significant promise as a prognostic biomarker, particularly in breast cancer." (PMID 40655141, 2025). "In breast cancer lysosomes have a key role in invasion mediated by the oncogenic transcription factor Myeloid Zing Finger 1 (MZF1)." (PMID 39243069, 2024). "The ability of MZF1 to bind to the TUBB3 loci was identified while looking for means to upregulate βIII-tubulin expression in HER2 positive breast cancer in an effort to induce sensitivity to the TBA, vinorelbine." (PMID 35573698, 2022). "Together, our findings identified NPPA as a prognostic marker, unveiled the biological function of NPPA, and explored the transcription modulation of NPPA by MZF1, which we believe would expand the horizon for breast cancer treatment." (PMID 34616853, 2021). "In osteoblasts, which are involved in osteolytic breast cancer metastasis, MZF1 has been shown to upregulate the expression of another EMT regulator, N-cadherin (CDH2)." (PMID 31963147, 2020). "In breast cancer, MZF1 activates the expression of cathepsin B to increase the invasion of cancer cells." (PMID 32042322, 2020). "MZF1 is involved in the etiology of many solid tumors, such as lung cancer 42, breast cancer 43, colorectal cancer 44, hepatocellular carcinoma 45, and cervical cancer." (PMID 32042322, 2020). "In a recent study that utilized ErbB2 positive breast cancer cells for phosphorylation analysis by Mass Spectrometry, 13 MZF1 phosphorylation sites were identified." (PMID 31963147, 2020). "Since MZF1 expression is negatively regulated by microRNAs let-7e and let-7d in breast cancer cells 60, the roles of let-7 family members in regulating MZF1-mediated aerobic glycolysis during NB progression warrant investigation." (PMID 32042322, 2020). "In non-invasive MCF7 breast cancer cells, MZF1 interacts with the CCCTC-binding factor (CTCF) via its acidic domain, which results in downregulation of the transcriptional activity of MZF1." (PMID 31963147, 2020).
breast carcinoma (continued). "In breast cancer, let-7e negatively regulates Myeloid Zinc Finger 1 (MZF1), a transcription factor that ultimately upregulates lysosomal cathepsins B and L in the context of ErbB2 positive breast cancer." (PMID 33066614, 2020). "High expression of MZF1, HK2, or PGK1 was also associated with poor survival of patients with breast cancer, endometrial carcinoma, glioma, head and neck carcinoma, lung cancer, lymphoma, pancreatic cancer, or renal clear cell carcinoma." (PMID 32042322, 2020). "In this study, we show that MZF1 expression is increased during breast cancer progression from normal epithelium to DCIS and IDC and that increased MZF1 expression can induce invasion of poorly invasive, MCF7 breast cancer cells in 3D Matrigel cultures." (PMID 29396433, 2018). "MZF1 expression was increased in a panel of breast cancer cells lines including MCF7, BT474, SK-BR-3, MDA-MB-231, MDA-MB-436, and MDA-MB-468 when comparing with non-cancerous, immortalized MCF10A cells." (PMID 29396433, 2018). "Taken together these results show that let-7d, let-7e, and let-7g can regulate MZF1 expression in various breast cancer cells directly via a functional let-7 target site in the MZF1 3′-UTR." (PMID 29396433, 2018). "Here we conclude that MZF1 expression is needed for the ErbB2-induced, invasion-promoting anterograde lysosomal trafficking in breast cancer cells." (PMID 29396433, 2018). "MZF1 is also expressed in various epithelial cancers, including breast cancer, where it promotes tumor progression." (PMID 29396433, 2018). "Taken together these results show that MZF1 is expressed in differentiated mammary epithelia and that its expression is increased in primary human breast cancer." (PMID 29396433, 2018). "The specificity of the MZF1 antibody was verified by IHC staining of paraffin sections of MCF7 breast cancer cells expressing doxycycline-inducible MZF1 and with a peptide competition assay." (PMID 29396433, 2018). "We compared MZF1 protein expression in tissue microarrays (TMAs) containing 321 samples of normal breast tissue and different grades of primary breast cancer by quantitative immunohistochemistry (IHC)." (PMID 29396433, 2018). "Other genes like MZF1 have been targeted for the inhibition of invasive growth of breast cancer due to MZF1 being one of the central node activated in breast cancer." (PMID 28607444, 2017). "We observed a positive correlation between moderate-to-strong PKCα and either Elk-1 and/or MZF-1 staining in breast cancer." (PMID 27542222, 2016). "MZF1 acts as an oncogene in the development of cervical cancer, colon cancer, breast cancer and lung cancer or a tumor suppressor gene in hematopoietic tumors and ovarian cancer." (PMID 27764784, 2016). "Furthermore, when MZF1 expression was silenced, a significant reduction in the proliferation of breast cancer cells was observed." (PMID 40655141, 2025). "Together, our study identified NPPA as a potential prognostic biomarker for breast cancer patients, whose downregulation is associated with an enhanced malignant behavior of breast cancer cells both in vivo and in vitro and identified the transcription regulation of NPPA by MZF1." (PMID 34616853, 2021). "Specific post-translational modifications of MZF1 are induced in invasive cancer, as is the case for breast cancer harboring ErbB2 activation, and these are necessary for the invasive signaling mediated via MZF1 in response to ErbB2 activation in breast cancer cells." (PMID 31963147, 2020). "Let-7 binds to the 3′-untranslated region of MZF1, and ectopic expression of let-7 microRNAs let-7d and let-7e can efficiently downregulate MZF1 and invasion of constitutively active ErbB2-expressing breast cancer cells." (PMID 31963147, 2020). "Indeed, increased expression of MZF1 protein levels has been detected in the study of 321 tissue microarray samples containing primary breast cancer and normal breast samples." (PMID 31963147, 2020).
breast carcinoma (continued). "MZF1 is needed for the invasion of ErbB2-expressing breast cancer cells." (PMID 31963147, 2020). "Interestingly, a complex formation between Elk-1 and MZF1 has been shown to enhance PRKCA expression in a synergistic manner and its expression correlates positively with the expression of Elk1 and MZF1 in various breast cancer cell lines." (PMID 31963147, 2020). "This all suggests that MZF1 has a role in the development of aggressive breast cancer." (PMID 31963147, 2020). "This may additionally lead to enhanced activation of other MZF1 target genes that are important for amplification of breast cancer signaling networks and promoting breast cancer cell migration and invasion, such as PRKCA." (PMID 31963147, 2020). "It showed that MZF1, upon activation by ErbB2 signaling, can induce the pericellular accumulation of lysosomes at the invadosome-like cellular protrusions in invasive ErbB2 expressing breast cancer cells, thereby initiating and promoting their invasion." (PMID 31963147, 2020). "Invasion of the MCF7 breast cancer spheroids expressing the trastuzumab-resistant p95 form of ErbB2 depends on the activation of a signaling network that culminates in the activation of MZF1." (PMID 31963147, 2020). "PAK4, a kinase that can phosphorylate MZF1 serine 27 in response to ErbB2 activation, is considered as a good target for the treatment of a variety of solid cancers including breast cancer, and its inhibition for this purpose has been patented by Hoffman-La Roche and Genentech." (PMID 31963147, 2020). "Conversely, we have previously shown that invasion of breast cancer cells expressing high levels of ErbB2 could be inhibited by reducing MZF1 expression with MZF1 siRNA13." (PMID 29396433, 2018). "Moreover, our finding that in breast cancer cells the level of MZF1 and consequently, the MZF1-controlled anterograde lysosome trafficking can be regulated by let-7, identifies a previously unnoticed function for this well-studied miRNA family." (PMID 29396433, 2018). "Thus, MZF1 performs similar functions in breast cancer cells as TFEB, also known as a master regulator of the Coordinated Lysosomal Expression and Regulation (CLEAR) network, has in normal cells." (PMID 29396433, 2018). "Furthermore, we show that MZF1 regulates lysosome trafficking in ErbB2-positive breast cancer cells." (PMID 29396433, 2018). "This suggests that lin28A could be involved in the regulation of MZF1 expression via let-7 in breast cancer." (PMID 29396433, 2018). "Similarly, MZF-1 can induce production of TGF-β1 in breast cancer and plays a critical role in osteopontin-induced mesenchymal-stem-cell to cancer-associated-fibroblast transformation." (PMID 27542222, 2016). "To determine whether the clinical relevance of the correlation between PKCα and Elk-1 and/or MZF-1 exists in breast cancer, we examined the expression of these proteins in tissue arrays by immunohistochemical (IHC) staining." (PMID 27542222, 2016). "By identifying MZF1 as a novel target of let-7, this study further suggests that the lack of let-7 suppression on MZF1, could result in MZF1 upregulation and thus contribute to oncogenesis and breast cancer progression." (PMID 29396433, 2018). "Myeloid Zinc Finger1 (MZF1) is an ErbB2-responsive transcription factor that promotes invasion of breast cancer cells via upregulation of lysosomal cathepsins B and L. Here we identify let-7 microRNA, a well-known tumor suppressor in breast cancer, as a direct negative regulator of MZF1." (PMID 29396433, 2018). "Thus, we utilized the mRNA expression array data from TCGA to investigate the correlation between MZF1 and lin28A and lin28B mRNA (LIN28A and LIN28B) in breast cancer and found that MZF1 expression correlates positively with the expression of lin28A, but not lin28B." (PMID 29396433, 2018).
breast carcinoma (continued). "In this study, we present a functional link between let-7 family members and breast cancer cell invasion, by identifying MZF1 as a novel target of let-7 and by connecting let-7 to the invasion-promoting lysosomal distribution of ErbB2-positive breast cancer cells via MZF1." (PMID 29396433, 2018). "Furthermore, clustering 13 breast cancer cell lines with shRNA scores of MZF1, SOX10 and ZEB1, could roughly distinguish TNBC cell lines from nTNBC cell lines." (PMID 28423538, 2017). "In breast cancer, transdifferentiation of BMSCs into distinct CAF subsets is mediated by myeloid zinc finger 1 (MZF1)-induced TGFβ1 through the osteopontin–TGF-β1 pathway." (PMID 40805183, 2025). "In breast cancer, bone marrow-derived mesenchymal stem cells (BM-MSCs) are recruited and transformed into distinct CAF subsets through the TGF-β1-mediated osteopontin-myeloid zinc finger 1 (MZF1) pathway." (PMID 34635121, 2021). "Osteopontin may play an important role in bi-directional communication between CAF and HNSCC cells, and in breast cancer models has been shown to induce transformation of mesenchymal stem cells into CAF, in a MZF1(myeloid zinc finger 1)-TGFβ1-dependent manner." (PMID 35048030, 2021). "Identification of MZF1 as an oncogenic target of PAK4, whose activity is important for invasiveness of ErbB2 positive breast cancer cells, suggests that PAK4 inhibitors might be useful for the treatment of cancers whose aggressiveness depends on MZF1." (PMID 31963147, 2020). "Moreover, a MZF1 target gene AXL, which can be activated upon lapatinib resistance in ErbB2 positive breast cancer cells, has been shown to induce EMT in breast cancer cells." (PMID 31963147, 2020). "The results presented here link MZF1 and let-7 to lysosomal processes in ErbB2-positive breast cancer cells that in non-cancerous cells have primarily been connected to the transcription factor EB." (PMID 29396433, 2018). "Nuclear factor erythroid 2-like 2 (NRF2) and myeloid zinc finger-1 (MZF-1) could impact cancer cell growth by transcriptionally regulating FPN, FTH, and FTL expression in prostate and breast cancer." (PMID 30591630, 2018). "Overactivation of ErbB2 signaling leads to activation of the transcription factor MZF1 which in turn increases the expression of the lysosomal cholesterol transporter NPC1 and activates macropinocytosis, increasing the macropinocytotic uptake of extracellular cholesterol in breast cancer cells." (PMID 39243069, 2024). "In addition, a decrease in the expression of AXL, a novel receptor tyrosine kinase known to be an essential EMT-induced regulator of breast cancer and regulated by MZF-1, was also observed, and the decrease can be reversed by rescuing MZF-1 expression with protease inhibitor." (PMID 27542222, 2016). "However, in our studies of MZF1 post-translational modification and their effect on protein stability, we found that in ErbB2-expressing breast cancer cells, MZF1 is a very stable protein and its stability was not affected by mutating its SUMO sites (Brix and Kallunki, unpublished observations)." (PMID 31963147, 2020).